CDKN2A (cyclin dependent kinase inhibitor 2A)
Diseases named in the same sentence as CDKN2A in open-access papers (continued):
Sharing a sentence is not in itself a finding about the gene and the disease.
tumor (continued). "It is reported to be in strong linkagedisequilibrium with cell cycle proliferatory genes such as cyclin dependantkinase inhibitors 2A and 2B (CDKN2A and CDKN2B).CDKN2A is basically a tumor suppressor gene and encodes twoproteins viz. p14ARF and p16." (PMID 32191788, 2020). "While CDKN2A expression was still present in the hemizygous case, a subsequent patient-derived xenograft (PDX) model established from this tumor showed full loss of expression, even extending to other nearby genes." (PMID 32313009, 2020). "CDKN2A is traditionally known as a tumor-suppressor gene coding for two proteins, including the p16INK4a and p14arf." (PMID 33553144, 2020). "CDKN2A (also known as p16), an autophagic gene, mainly regulates the G1/S cellular cycle process, which is known as a tumor suppressor gene." (PMID 32998713, 2020). "Next, we assessed tumour heterogeneity and evolution with respect to p16 IHC and CDKN2A copy number alteration from patients for whom there was more than one sample available including the primary tumour." (PMID 31916407, 2020). "CDKN2A is able to induce cell cycle arrest at the G1 and G2 phases and thus has a tumor-inhibitory effect." (PMID 32420374, 2020). "CpG island methylator phenotype (CIMP) can result in the silencing of key genes important for tumor progression, including the tumor‐suppressor gene, CDKN2A, and the DNA mismatch repair gene, MLH1." (PMID 33005848, 2020). "Mice carrying an extra copy of Cdkn2a show increased resistance to cancer, consistent with the known tumor-suppressive role of p1618." (PMID 32483135, 2020). "CDKN2A encodes two proteins, namely, the INK4 family members p16 and p14arf, and both of these proteins act as tumor suppressors by regulating the cell cycle." (PMID 32670354, 2020). "Other work has recently demonstrated cooperation between Nf2 and Cdkn2a in MM development in asbestos-exposed Nf2+/−;Cdkn2a+/− mice, which exhibited significantly hastened tumor onset and disease progression vs. similarly exposed Nf2+/− and wild-type cohorts." (PMID 32117751, 2020). "PcG complexes target the Cdkn2a locus and regulate HSCs by acting as critical failsafe against the premature aging induced by the p16Ink4a and p19Arf tumor suppressors." (PMID 33292805, 2020). "Tumor size: CDKN2A methylation and reduced expression of p16 are significantly related to larger tumor size." (PMID 32201880, 2020). "We also found LOH at the CDKN2A gene locus and abundant Cyclin D1 expression in the tumor in this VHL patient." (PMID 31673890, 2020). "If CCND1 amplification was present in the primary tumours, CDKN2A homozygous deletion appeared in the bone metastases (HBCx-131) or in the PDX (HBCx-134), in patients who recurred 10 years and 1 year, respectively, after treatment with an aromatase inhibitor." (PMID 32792481, 2020). "Regarding tumor heterogeneity, we have shown in our study that MTAP and CDKN2A genomic pattern when analyzed by FISH can be a mixture of retained (no loss), homozygous or hemizygous loss signal patterns within one tumor." (PMID 33304846, 2020). "Two important tumor-suppressor genes, CDKN2A (chromosome 9p21.3) and CDKN2B (chromosome 9p21.3), were deleted in all clusters except for II." (PMID 33194713, 2020).
tumor (continued). "CDKN2A is a tumor-suppressor gene that is involved in the regulation of cell cycle and that encodes four transcript variants: p16INK4A, p14ARF, p12, and p16γ." (PMID 33322357, 2020). "Because of the interaction between HPV E7 protein and host cells, CDKN2A mRNA upregulation was also observed in HPV+ tumours arising in the oropharynx." (PMID 32684626, 2020). "Copy number alterations were retained across several tumor-organoid pairs include CDKN2A, ERBB2, NF1, and SNX31." (PMID 32774159, 2020). "It is possible this discordance in CDKN2A deletion results over time is due to differences in sampling locations within tumor specimens and/or between tumor and closely surrounding or contaminated normal brain tissue." (PMID 33153497, 2020). "The pathways induced by these stimuli finally converge in a set of senescence genes, the best known of which are the tumor suppressors Cdkn2a-p16, Cdkn2a-p19, Cdkn1b-p27, Cdkn2b-p15 or Cdkn1a-p21, resulting in proliferative arrest." (PMID 32584785, 2020). "Cdkn2a acts as a tumor suppressor in ALL through regulation of the cell cycle and Tmem119 is involved in osteoblast differentiation." (PMID 33154494, 2020). "In contrast to primary tumors, high levels of homozygous CDKN2A deletion occurred at a much higher relative frequency in recurrent tumor specimens." (PMID 33081848, 2020). "Whereas most tumor suppressor pathways seem difficult to target, CDKN2A suggests straightforward possibilities." (PMID 30890123, 2019). "UHRF1 is also associated with epigenetic silencing of various tumor suppressors and other tumor-related genes, including CDKN2A, RB, BRCA1, RASSF1, PPARG, APC, CDH1, and RGS2." (PMID 31064417, 2019). "Fenofibrate reduced the expression of the senescence marker CDKN2A in SF cultures, confirming previous findings in tumour cell lines, although the mechanism is still unclear since we did not observe increased death in fenofibrate-treated senescent SF." (PMID 31708994, 2019). "Our results show that tumor mutational burden, CIN markers, and co-occurring CCND1 and CDKN2A mutations are associated with chemoradiotherapy outcomes in advanced stage oro- and hypopharyngeal HNSCC patients, thereby highlighting their prognostic potential." (PMID 30934880, 2019). "Of the 22 upregulated genes, obASCs upregulated estrogen-related genes that have been shown to promote tumor growth, such as ESR2; as well as cell-cycle-related genes associated with proliferation, such as CDKN1C and CDKN2A." (PMID 30897853, 2019). "For the CNVs of CDKN2A and CDKN2B in tumor tissue, we found that CDKN2A or CDKN2B loss was detected in 27% (44/161) of the ESCC samples." (PMID 31700061, 2019). "As expected, in PDCX-ZEC145 models with CDKN2A and CDKN2B loss, palbociclib given at a 75 mg/kg dose demonstrated a remarkable inhibition of tumor growth." (PMID 31700061, 2019). "The 9p21.3 region contains well-known tumor suppressor genes including the cyclin-dependent kinase inhibitor 2A/B (CDKN2A/B) gene." (PMID 38370916, 2019). "CHEK2 and CDKN2A are known tumor suppressors, and TMPRSS2 and ERG are frequently involved in translocation events forming fusion oncogenes in certain cancers." (PMID 30736820, 2019). "The CDKN2A gene encodes the P16(INK4A) and p14(ARF) proteins, both of which act as tumor suppressors." (PMID 31681791, 2019).
tumor (continued). "From relapsed tumor procured at autopsy, we established a cell line retaining the BRAF V600E mutation, TERT promoter mutation and CDKN2A/2B loss." (PMID 31345255, 2019). "Given that promoter hypermethylation is an alternative method to inactivate tumor-suppressor genes in a variety of malignancies, we evaluated the methylation status of 93 CDKN2A and CDKN2B genes." (PMID 30635552, 2019). "Next-generation sequencing of tissue samples results showed CDKN2A/B loss, MSI-stable, TMB (tumor mutation burden)-low, and variants in the following genes: ATM, BARD1, FAT1, FLT4, KEAP1, MLL3, PIK3, and TAF1." (PMID 30739492, 2019). "A 2003 study detected methylation of the CDKN2A promoter in the ctDNA of 47% of HCC patients where promoter methylation had been observed in the tumor." (PMID 31608239, 2019). "Given that CDKN2A is a crucial component of the RB1 pathway, perturbations in the tumor suppressor pathway will result with deletion of CDKN2A." (PMID 31906059, 2019). "The immunohistochemical expression of CDKN2A is higher in squamous cell carcinoma compared to other HPV-related tumour types." (PMID 31319555, 2019). "Among the most deleted genes, we observe well-known tumor-suppressor genes, such as CDKN2A and PTEN." (PMID 31379928, 2019). "Another tumor suppressor gene that is commonly mutated, CDKN2A, encodes two other cell cycle regulatory proteins, p16 and p14ARF." (PMID 31608239, 2019). "The CDKN2A/B locus encompasses three major tumor suppressors juxtaposed and joined into a p16-CDKN2A/p15-CDKN2B/p14-ARF gene cluster." (PMID 31438464, 2019). "Accordingly, the INK4b/ARF/INK4a locus is deleted or downregulated in about 40% of human cancers, mainly related to the tumor suppressive function of CDKN2A and CDKN2B; conversely, ANRIL itself shows a pro-oncogenic activity." (PMID 31694342, 2019). "Genes of cell cycle progression such as CDKN2A and RB1 were more frequently mutated in LUSC tumours." (PMID 31461552, 2019). "Chromosome 9p21.3 resides in a region distant from known coding regions, with tumor suppressor genes of cyclin-dependent kinase inhibitors (CDKN2A and CDKN2B) and methylthioadenosine phosphorylase." (PMID 30921371, 2019).
tumor (continued). "Chromosome 9p contains numerous tumor-associated genes, such as PAX5 at 9p13.2, CDKN2A, CDKN2B, MTAP, IFN, MLLT3, PTPLAD2 at 9p21.3, and JAK2 at 9p24.1." (PMID 31168295, 2019). "The two ESCC PDCs (ZEC145, with CDKN2A/2B loss, and ZEC166, harboring wild-type CDKN2A/2B) were both capable of generating tumor xenografts." (PMID 31700061, 2019). "Other studies by the same group detected CDKN2A promoter methylation in around 80% of HCC patients where methylation was present in the tumor." (PMID 31608239, 2019). "Although a mutation in the Rb pathway is present in most GBMs, the RB gene itself is infrequently mutated, and instead, mutations in cyclin-dependent kinase inhibitor 2A (CDKN2A, 50% of tumours) are particularly common." (PMID 31505839, 2019). "Although the CDKN2A/B locus is deleted or silenced in approximately 40% of human cancers, related to the tumor suppressive actions of CDKN2A and CDKN2B, ANRIL itself has pro-oncogenic properties." (PMID 30087655, 2018). "Our results indicate that CNV analysis of tumor and matched cell-line samples were concurrent and both indicated CDKN2A deletion." (PMID 30301262, 2018). "The deletion of CDKN2A/ARF has also been correlated with GBM tumors displaying prominent adipocytic-like tumor cell differentiation." (PMID 30200436, 2018). "Tumours from the basal squamous group on average showed the highest CDKN2A expression and tumours from the luminal group had a comparably low CDKN2A expression." (PMID 30258198, 2018). "Both in NMIBC and in MIBC there was a significant coincidence of CDKN2A deletions and activating mutations of FGFR3 and NMIBC tumours with this feature had an increased progression rate." (PMID 30258198, 2018). "The activation of STAT3, STAT5B, and CDKN2A promotes a state of equilibrium and has tumor suppressive activities." (PMID 30325954, 2018). "This study suggests that the CNV of CDKN2A is identifiable in MPM tumor samples and derivative cell lines alike using ddPCR." (PMID 30301262, 2018). "Fitting to this TCGA basal squamous tumours have the highest CDKN2A expression, whilst tumours from the luminal TCGA subtype group had an exclusively low expression." (PMID 30258198, 2018). "In order to determine if CDKN2A expression also correlated with E2 gene status, we measured p14ARF and p16INK4A RNA levels in our tumor samples." (PMID 29451891, 2018). "Stratification for CDKN2A expression also showed a significantly lower expression of ESR2 in CDKN2Ahigh tumours (p < 0.001)." (PMID 30258198, 2018). "The proteins encoded by CDKN2A and CDKN2B are tumor suppressors with well-established roles in cell proliferation, apoptosis, senescence and aging." (PMID 30087655, 2018). "Curiously, in the Alb-R26Met cancer model Cdkn2a, rather considered as a tumour suppressor, is overexpressed and hypermethylated in its gene body CGI, whereas no methylation changes were observed in its promoter CGI." (PMID 30089774, 2018).
tumor (continued). "Tumor progression was associated with an imbalance in the acetylation and deacetylation of histones and increasing the HDAC levels potentially repressed the tumor suppression genes RB1 and CDKN2A, initiating tumor formation." (PMID 29301348, 2018). "Nonetheless, non-tumor lung expression of CDKN2A and P63 was significantly higher in LC-COPD than LC patients." (PMID 29371906, 2018). "For example, in CAM277, a one-nucleotide deletion (Chr9:21972087) of CDKN2A was detected in 8 of 33 total reads in the primary tumor; in contrast, it was found in 23 of 23 total reads in the derived organoid culture." (PMID 30061675, 2018). "Given that aberrant methylation of p16ink4 promoter is frequently observed in adenocarcinoma arising from the gastrointestinal tract, MSP experiments were performed and CDKN2A (p16ink4) promoter hypermethylation was detected in 4 out of 5 tumour samples." (PMID 29700411, 2018). "Due to the limited somatic mutations in each NPC-PDX tumor sample, we incorporated all the SNVs identified in 282 genes as well as CCND1 and CDKN2A to perform pathway analysis (Metacore)." (PMID 30236142, 2018). "Increased relative cerebral blood volume and cerebral blood flow within enhancing tumor were associated with EGFR amplification and CDKN2A loss." (PMID 29459844, 2018). "Variant allele of rs3731249 induced amino acid change in p16INK4A, protein product of CDKN2A, and reduced the tumor suppression effect of p16INK4A, suggesting rs3731249 act as a causal variant for ALL susceptibility." (PMID 29654170, 2018). "NPC tumors are characterized as tumors with relatively low single nucleotide mutation but with frequent hypermethylation, amplification of CCND1, deletion of tumor suppressor genes such as CDKN2A and 2B, and other chromosome abnormalities." (PMID 30236142, 2018). "Tumors must be pRb wild type and carry inactivation of CDKN2A/B or C in the tumor by homozygous deletion." (PMID 30631751, 2018). "A recent study identified CDKN2A as a tumor suppressor whose inactivation promoted homotypic cell-in-cell formation in human cancer cells." (PMID 30555633, 2018). "Several key genetic alterations are associated with the development and progression of MM including mutations of the CDKN2A/ARF, NF2, and BAP1 tumor-suppressor genes." (PMID 29565815, 2018). "The intricate pattern of tumor-specific APA regulation of CDKN2A in KIRC is also identified in COAD, KICH, KIRP, LIHC, PRAD and THCA, but describing such regulation by 3’ UTR length modulation would be inadequate." (PMID 30005633, 2018). "ELAVL2 is located at the chromosome band 9p21.3, where CDKN2A (a well-known tumor suppressor) is also located." (PMID 28035070, 2017).